BTG2 (BTG anti-proliferation factor 2)
Diseases named in the same sentence as BTG2 in open-access papers (continued):
Sharing a sentence is not in itself a finding about the gene and the disease.
tumor (continued). "A number of observations point to a tumor suppressive role for BTG1 and BTG2 in a range of malignancies, although in most examples, the exact mechanism by which BTG1 or BTG2 contribute to tumor development/progression requires further investigation." (PMID 30350856, 2019). "Luminal type tumours had higher gene expression levels of BTG2 compared to HER2-like and basal type tumours (p 1.6e-10) and our current study has revealed a strong correlation between BTG2 expression and visceral metastasis (p 2.13e-08)." (PMID 30961553, 2019). "Our results demonstrated that BTG2 expression was reduced in invasive, primary, and recurrent NFPA, suggesting a tumor-suppressor function." (PMID 31223310, 2019). "miR-21 has been identified to target at the tumor suppressing genes, such as the protein tyrosine phosphatase (PTEN), programmed cell death 4 (PDCD4), and B cell translocation gene 2 (BTG2)." (PMID 31032345, 2019). "Compared to the expression levels in normal tissue, other genes, such as ADRB3, BTG2, DUSP4, RAD51 or FBLX7, were downregulated in specific tumor types, and ANG, ESD and STL7 were downregulated in most tumor types." (PMID 31159852, 2019). "To compare the BTG2 expression difference, we extracted 74 early‐stage cases from the GDC cohort with data on both tumour and adjacent normal tissue gene expression." (PMID 29656435, 2018). "Additionally, the expression of BTG2 is significantly correlated with the degree of tumor differentiation, indicating that ESCC patients with low BTG2 expression tend to have poorly differentiated tumors." (PMID 41441930, 2025). "Immunohistochemical analysis revealed that NOX2 expression was significantly higher in tumor tissues compared to adjacent non-cancerous tissues, while BTG2 expression was markedly lower in tumor tissues." (PMID 41441930, 2025). "To further investigate the molecular characteristics and the role of enlarged mast cells which are particularly prevalent in the tumor and TLN tissues of NAC-resistant patients, we identified the low expression of BTG2 as the predominant differential molecular feature in these cells." (PMID 40313959, 2025). "Additionally, the protein expression levels of SLA, BTG2, DDIT4, TUBA4A, and PTTG1 in LUAD tumor tissues and normal tissues were investigated using the Human Protein Atlas (HPA) database." (PMID 38200058, 2024). "Furthermore, the expression of anti-tumorigenic genes (ERG2, ERG3, and BTG2) was promoted by the interaction between CX3CR1+ macrophages and NR5A1+ tumor cells through the ligand-receptor INHBA-ACVR1B pair." (PMID 38658971, 2024). "Indeed, Nkx2-2as functions as a ceRNA, sequestering miR-103/107 and miR-548 that target BTG2/Tis21/PC3 and LATS1/2 tumor suppressors, consequently its downregulation fosters tumor growth both in vitro and in vivo." (PMID 38004481, 2023). "All these indicate that BTG2 induces cell cycle arrest but has no apparent effects on tumor cell growth." (PMID 36157236, 2022). "MeRIP-qPCR results validated that the m6A methylation level of BTG2 was significantly decreased in tumor tissues compared to normal tissues." (PMID 36591524, 2022). "We further constructed gene modules in AT2 (LUAD) and basal (LUSC) cells, which revealed that many tumor-related genes in cells from stage-I patients, including PIGR, AZGP1, BTG2, EGR1, and LMO3 in AT2 cells from LUAD, and AQP3, SPHK1, PPT1, and PDIA6 were found in basal cells from LUSC." (PMID 35027529, 2022). "Moreover, upregulated expression of BTG2 inhibited the migration, invasion, EMT and glycolysis in lung adenocarcinoma (LUAC) cells and tumor growth." (PMID 34217312, 2021). "BTG2 and BTG1 are tumor-suppressor genes and members of the human BTG/TOB family." (PMID 33777778, 2021).
tumor (continued). "In our study, we found hundreds of genes with a difference in expression by more than twofold after HELLS knockdown in the three PC cell lines; among them, 23 genes differed among the cell lines, including several tumor suppressor genes, such as TGFBR3, BTG2, and DKK1." (PMID 33280236, 2021). "In our work, we demonstrated that BTG2 suppressed EMT and metastasis in HCC tumours." (PMID 32746503, 2020). "Importantly, we identified BTG2 as a downstream target of SRXN1; This provides a novel layer of evidence for the tumour‐promoting function of SRXN1 and its regulatory network in HCC tumour metastasis." (PMID 32746503, 2020). "In addition, miR-21-5p was controlled by one gene called miR-21 and in previous studies, miR-21 has been proved to be capable of targeting many tumor suppressors such as PTEN, RECK, BTG2 and TP63." (PMID 30134821, 2018). "Our results show that downregulation of Btg2 is not sufficient but is necessary for tumor progression since the re-introduction of Btg2 in fully progressed tumors dramatically impairs their gliomagenic potential." (PMID 23203087, 2012). "On the other hand, TIS21/BTG2/PC3 can inhibit the degradation of cyclin A and cyclin B1 in G2/M phase when stimulated by epidermal growth factor (EGF) at high concentration, and directly combine with Cdc2, thus hindering cell mitosis and increasing the aging and death of tumor cells." (PMID 37794858, 2023). "It is known that in different human cancers Btg2 (human ortholog of the mouse gene Tis21) inhibits the processes of cell proliferation, survival and metastasis by suppressing the PI3K/AKT/mTOR pathway, since the Btg2 protein acts as a negative regulator of AKT in both tumor cells and normal ones." (PMID 34395258, 2021). "Using our previous microarray dataset, we determined that the expression of EZH2, RRM1 and FOXM1 was significantly increased in tumor compared with the non-tumor lung tissue and the expression of BTG2, NFIB and SELENBP1 was significantly decreased in the tumor compared to non-tumor." (PMID 30458017, 2018). "Both NOX2 and BTG2 were localized to the cell membrane and/or cytoplasm, with expression observed in both ESCC tumor cells and adjacent non-cancerous cells." (PMID 41441930, 2025). "BTG2, p73, and XPC were up-regulated, however the differences in these between 177Lu-trastuzumab and 177Lu-HuIgG treated tumor tissue was not significant." (PMID 27196891, 2016). "IMR90 cells, on the other hand, seemed to be impacted by a different panel of genes, BTG2, FBXW7, NDUFAF2, PHLDA1, and DMD, whose knockdown did not have a significant impact in the two tumor cell lines, suggesting cell line-specific effects." (PMID 24009623, 2013). "In addition, the expression of BTG2, CD69, GPC3, and IL7R were considerably elevated in tumor stages III-IV as opposed to tumor stage I-II (p < 0.05)." (PMID 34881236, 2021).
cancer (88 papers, 2010 to 2025). A tumor composed of atypical neoplastic, often pleomorphic cells that invade other tissues. "BTG2 has been implicated as a tumor suppressor gene as it is frequently deleted or mutated in cancer malignancies." (PMID 35053370, 2022). "BTG1 and BTG2 have been found to be frequently downregulated or mutated in several types of cancers, and the decreased expression of BTG1 and BTG2 is positively associated with malignant cell behavior and poor outcome in cancer patients." (PMID 32093041, 2020). "Twist1, a key transcription factor regulating epithelial–mesenchymal transition and cancer metastasis, is highly expressed in invasive cancers in contrast to the loss of BTG2/TIS21 expression." (PMID 31138781, 2019). "IPA at 4 h revealed that 7 genes [Btg2, Ccng2, Cdkn1a, Gadd45b, Gadd45g, Phlda3, and Mdm2] of 18 genes, which showed statistically significant increases, were associated with cancer, cell cycle, cell death and survival, and cellular growth and proliferation." (PMID 27482301, 2016). "Btg1 and Btg2 encode highly homologous proteins that are broadly expressed in different cell lineages, and have been implicated in different types of cancer." (PMID 26218146, 2015). "An immunohistochemical analysis in prostatectomy specimens demonstrated an association of low BTG2 protein expression with a higher clinical stage of prostate cancer and a shorter, cancer progression-free period." (PMID 26690121, 2015). "In addition, BTG2 is a gene enriched in the Hallmark of angiogenesis and platelets, whose downregulation is directly related to the invasion of cancer cells." (PMID 36138770, 2022). "Epithelial-mesenchymal transition (EMT) was conferred by loss of BTG2 in various cancer." (PMID 33791222, 2021). "There are currently no reported studies linking BTG2 expression to the degree of cancer differentiation, which is consistent with the anti-proliferative effects of BTG2." (PMID 41441930, 2025). "The relatively high mutation frequency of BRCA in CNV analysis across 31 types of cancers, especially in genes such as ABL2 and BTG2, further underlines the extreme complexity of BRCA patient heterogeneity." (PMID 40332226, 2025). "BTG2 has roles in cell cycle control, cell differentiation, proliferation, DNA damage repair, and apoptosis in cancer cells, and recently, it has been reported as a radio-responsive gene." (PMID 38256047, 2024). "We observed that in 83 pairs of samples, the BTG2 expression in cancer tissue was significantly lower than that in adjacent tissues." (PMID 36841760, 2023). "BTG2 is a downstream target molecule of miR-15a-5p, and many studies have shown that BTG2 regulates FAK expression in different cancers." (PMID 36841760, 2023). "In particular, the expression of Btg2, known as a tumor suppressor factor in various cancers, was markedly induced by combination treatment." (PMID 36765032, 2023). "Aberrantly expressed Btg2 was reported to regulate cell proliferation, the cell cycle, cell apoptosis, and tumorigenicity in several kinds of cancer." (PMID 35045793, 2022). "At the same time, the expression of BTG2 in many types of cancer cells has varying degrees of reduction or even direct deletion, while the expression level of BTG2 gene in many corresponding normal cells is relatively higher." (PMID 36591524, 2022). "BTG2 has been found to be expressed at low levels in a variety of cancer cells, which has potential in the development and subsequent progression of tumors." (PMID 36591524, 2022). "BTG2 has been found to be expressed at low levels in a variety of cancer, which has potential role in the development and subsequent progression of tumors." (PMID 36591524, 2022). "BTG2, IL7R, and LAMP3 are significantly downregulated in carcinoma samples, and their high expressions are markedly implicated with more prolonged overall survival, which is consistent with our study." (PMID 35372503, 2022).
cancer (continued). "The present work validated that miR-92a-3p played a cancer-promoting role in BC, and further confirmed that BTG2 was a direct miR-92a-3p target." (PMID 34082648, 2021). "Many studies have shown that regulation of the expression of BTG2 protein can effectively inhibit cancer initiation and development." (PMID 34187411, 2021). "The findings imply the significant role of BTG2 that can prevent cancer progression via inhibition of cancer cell invasion and metastasis into surrounding tissues." (PMID 31138781, 2019). "In summary, SNHG5 inhibits EC cancer cell development by interacting with miR-25-3p, while miR-25-3p exhibits opposite effect on EC development by targeting BTG2 mRNA." (PMID 31885582, 2019). "Dysregulation of BTG2 expression has been previously reported in certain types of human cancers; nevertheless, its molecular functions in EC and its regulation remain poorly understood." (PMID 31885582, 2019). "Two recent studies reported that B‐cell translocation gene 2 (BTG2) plays an important role in cancer progression." (PMID 29656435, 2018). "B‐cell translocation gene 2 (BTG2) is a tumour suppressor protein known to be downregulated in several types of cancer." (PMID 29656435, 2018). "Following bioinformatics prediction of miR-21 targets, experiments were performed to investigate expression of B cell translocation gene 2 (Btg2), a key gene involved in cell differentiation, proliferation, DNA damage repair, and apoptosis in cancer cells." (PMID 28944400, 2018). "Results of immunoblotting assays also indicated that expression of BTG2 was lower in the cancer part than paired normal tissues." (PMID 29239139, 2018). "As BTG2 has been reported to relate to cancer via various biological mechanisms, it has a potential to be a target gene for precision treatment." (PMID 29656435, 2018). "The relationship between BTG2 and miRNA in human cancer has attracted wide interests recently, and it has also been reported that miR-25 can directly bind BTG2 in NSCLC cells." (PMID 29310680, 2018). "Several members including TOB1-2 and BTG2-3, exhibited significant expression differences between cancer and normal tissue groups in defined cancers." (PMID 28922388, 2017). "Consistent with previous studies, our expression analyses showed that the mRNA levels of TOB1 and BTG2 were reduced in most cancers compared to normal tissues." (PMID 28922388, 2017). "Compared to normal tissues, BTG2 was reduced in tumors, demonstrated by 52 analyses involving 13 kinds of cancers, only 12 studies showed an increased level." (PMID 28922388, 2017). "We observed that the mRNA expression levels of TOB1-2 and BTG2 were decreased in most cancers compared with normal tissues, while BTG3 was upregulated in most cancers." (PMID 28922388, 2017). "BTG2 expression is deregulated in various cancers, consistent with its role as a tumor suppressor protein." (PMID 26818199, 2016). "BTG2 expression is found to be decreased in a variety of human cancers and plays important roles in controlling cell cycle progression, cell differentiation, DNA damage repair, and apoptosis." (PMID 26690121, 2015). "In the present study, we presented evidences on the crosstalk between PI3K-Akt and NFκB pathways after ectopic and endogenous BTG2 expressions in normal and cancer cells via activation of Akt1 and degradation of IκBα protein." (PMID 24047462, 2013). "Both BTG1 and BTG2 are closely correlated with the prognosis of cancer patients." (PMID 40918450, 2025).
cancer (continued). "Notably, the upregulation of miR-93-5p exhibited a greater prominence in MIBC than in NMIBC, potentially through the targeted inhibition of B-cell translocation gene 2 (BTG2) to promote cancer cell proliferation, migration, and invasion." (PMID 38808545, 2024). "Upregulation of BTG2 inhibits cancer migration, invasion, EMT and, glycolysis." (PMID 36639776, 2023). "As expected, we identified that the upregulation of three collagen genes (COL1A1, COL3A1, and COL1A2), BTG2, and JUNB might be responsible for the radiation-associated secondary cancers in patients with BCa." (PMID 35274048, 2022). "More importantly, knockdown of BTG2 counteracted the inhibiting impact that miR-92a-3p inhibitors had on the malignant biological behaviors of BC cells, while overexpression of BTG2 partially attenuated the cancer-promoting effect of miR-92a-3p in BC." (PMID 34082648, 2021). "Furthermore, there is evidence that expression levels of BTG1 and BTG2 can be used as prognostic biomarkers in various cancers." (PMID 30350856, 2019). "In addition, we will highlight the molecular mechanisms and biological consequences of BTG1 and BTG2 deregulation during cancer progression and elaborate on the potential clinical implications of these findings." (PMID 30350856, 2019). "Secondly, BTG2 is involved in the development and differentiation of cancer cells that could promote retinoic acid‐induced differentiation in haematopoietic cells." (PMID 29656435, 2018). "BTG2 is involved in several important cancer‐related pathways." (PMID 29656435, 2018). "While BTG2 plays an important role in cellular differentiation and cancer, its precise molecular function remains unclear." (PMID 26912148, 2016). "In turn, overexpression of BTG2 triggered G1/S cell cycle arrest, induced subsequent apoptosis, and inhibited C-myc activation following Ras/MEK/ERK signaling pathway, which involved in the biological effects of miR-27a-3p/BTG2 axis on gastric carcinogenesis and cancer progression." (PMID 27409164, 2016). "Btg1 and Btg2 proteins regulate various cellular processes including proliferation, differentiation and apoptosis, while deregulated expression has been observed in various cancers, including B cell malignancies." (PMID 26218146, 2015). "In addition, BTG2 regulates cancer cell migration via regulations of ROS level and chemokines Cxcl3 and Cxcl12." (PMID 24047462, 2013). "To further investigate the molecular mechanisms underlying BTG2’s regulation of mast cell migration, we conducted Gene Set Enrichment Analysis (GSEA) on the signaling pathways of mast cells isolated from a drug-resistant cancer model using previously generated scRNA sequencing data." (PMID 40313959, 2025). "Likewise, miR-6875-3p affects cancer cells' invasiveness via BTG2." (PMID 36816363, 2023). "Hence, BTG2 participates in some pathways that are crucial for cancer development and progression." (PMID 29656435, 2018). "Therefore, we speculate that BTG2 might play a significant role in the modulation of mitochondrial defect in cancer cells." (PMID 24047462, 2013).